NTF3 (neurotrophin 3)
Description:
Seems to promote the survival of visceral and proprioceptive sensory neurons.
Synonyms: NT-3; NGF-2; NGF2; HDNF; NT3
Tractability: Antibody: its Gene Ontology location is reachable by antibodies, with high confidence; UniProt places it where antibodies can reach, with medium confidence; UniProt predicts a signal peptide or a membrane-spanning region.
Gene: Protein-coding gene on chromosome 12 (5,432,108 to 5,521,536, forward strand). Ensembl gene ENSG00000185652.
Subcellular location: Secreted
Subcellular location (Human Protein Atlas): Vesicles; Predicted to be secreted
Pathways (Reactome):
Signal Transduction: Activated NTRK3 signals through PI3K; Activated NTRK3 signals through PLCG1; Activated NTRK3 signals through RAS; NTF3 activates NTRK2 (TRKB) signaling; NTF3 activates NTRK3 signaling; PI5P, PP2A and IER3 Regulate PI3K/AKT Signaling; PIP3 activates AKT signaling; Signaling by NTRK3 (TRKC)
Disease: Constitutive Signaling by Aberrant PI3K in Cancer
Gene Ontology:
Molecular function: chemoattractant activity; growth factor activity; protein binding; nerve growth factor receptor binding; signaling receptor binding; neurotrophin receptor binding
Biological process: cell surface receptor protein tyrosine kinase signaling pathway; induction of positive chemotaxis; positive regulation of cell migration; positive regulation of cell population proliferation; positive regulation of MAPK cascade; positive regulation of phosphatidylinositol 3-kinase/protein kinase B signal transduction; positive regulation of receptor internalization; regulation of apoptotic process; cell-cell signaling; modulation of chemical synaptic transmission; negative regulation of neuron apoptotic process; nerve development; nerve growth factor signaling pathway; nervous system development; neuron projection morphogenesis; signal transduction; positive chemotaxis
Cellular component: extracellular region; synaptic vesicle
Genetic constraint (gnomAD): Loss-of-function variants: 8 observed, 27.74 expected, observed/expected ratio (o/e) 0.29, 90% interval 0.17 to 0.52. The upper end of that interval is the gene's LOEUF score, 0.52, which puts it in group 2 of 6, group 1 being the genes least tolerant of losing a copy. Missense variants: 276 observed, 371.39 expected, observed/expected ratio (o/e) 0.74, 90% interval 0.67 to 0.82. Synonymous variants: 154 observed, 154.08 expected, observed/expected ratio (o/e) 1, 90% interval 0.88 to 1.14.
Homologues: Orthologues: macaque NTF3 (99% identical), dog NTF3 (96% identical), mouse Ntf3 (96% identical), rat Ntf3 (96% identical), chimpanzee NTF3 (96% identical), guinea pig NTF3 (96% identical), rabbit NTF3 (95% identical), pig NTF3 (91% identical), tropical clawed frog ntf3 (80% identical), zebrafish ntf3 (49% identical). Paralogues in human: NGF (39% identical), BDNF (33% identical), NTF4 (33% identical).
Diseases named in the same sentence as NTF3 in open-access papers:
NTF3 is named in the same sentence as 112 diseases in open-access papers, as found by Europe PMC text mining. Sharing a sentence is not in itself a finding about the gene and the disease. The quoted sentences say what the papers report.
depression (14 papers, 2014 to 2025). "Here, we report that Wfs1, a gene that can cause depression, is co-expressed with Ntf3, Penk, and Wnt7a in supragranular 2/3 pyramidal neurons in the mPFC." (PMID 26371510, 2015). "Additionally, the genesis of depressive disorders is also believed to be caused by low concentrations of the third neurotrophin (NTF3), and cerebrolysin can imitate its action." (PMID 40722733, 2025). "Numerous studies have shown that the expression of BDNF and NTF-3 are key targets related to the pathophysiology of depression and anxiety disorders." (PMID 36982280, 2023). "The aim of this study is to examine the factors that contribute to anxiety and depression in individuals undergoing maintenance hemodialysis (MHD), as well as their association with serum levels of brain-derived neurotrophic factor (BDNF), neurotrophin-3 (NT-3), and serotonin (5-HT)." (PMID 37750080, 2023). "In a rat model of male hypogonadism, resveratrol alleviated depression-like behaviors via increasing hippocampal and prefrontal cortical levels of BDNF and neurotrophin-3." (PMID 36358502, 2022). "In a mouse model of CUMS-induced depression, sesamin improved depressive symptoms by increasing neurotrophin expression levels, such as BDNF and neurotrophin-3." (PMID 36358502, 2022). "However, some studies have shown that serum levels of GDNF, NGF, and NTF3 in patients with major depression are not significantly different." (PMID 37509026, 2023). "In short, Geum japonicum, garlic essential oil, fish oil, conjugated linoleic acid, and anthocyanin could ameliorate depression through increasing the production of BDNF, nerve growth factor, and neurotrophin-3, and their effects and mechanisms should be further investigated by clinical trials." (PMID 36358502, 2022). "Furthermore, in mouse studies, SNK ingestion enhanced mRNA expression of neurotrophic factor (BDNF), neurotrophin-3, and gamma-aminobutyric acid (GABA) receptors under stress-free and chronic social stress conditions, and showed a tendency to improve learning ability and depression-like behavior." (PMID 35897310, 2022).
Anxiety (9 papers, 2013 to 2025). Intense feelings of nervousness, tension, or panic often arise in response to interpersonal stresses. "Indeed, recent evidence from our laboratory and others associates dysregulated signalling through neurotrophin-3 and its receptor TrkC with the pathophysiology of anxiety and fear-related disorders." (PMID 36882590, 2023). "Additionally, vitamin D disrupts the integrity of neurons by downregulating neurotrophic factors (neurotrophin-3 and neurotrophin-4) in the hippocampus and neocortex, causing anxiety." (PMID 37273529, 2023). "Along these lines, Fox and colleagues (2019) performed RNA-sequencing of dorsal amygdala tissue, which suggested that specific neuroplasticity-related processes, involving neurotrophic factor-3 (NTF3), may play a role in decreasing anxiety-like behavior." (PMID 33794355, 2021). "Mice genetically overexpressing the receptor for neurotrophin 3, TrkC, show increased anxiety-like behavior, as well as increased LC neuronal density, suggesting that some degree of positive feedback might exist between stress, neurotrophin 3 signaling, and LC plasticity." (PMID 30008741, 2018). "In this study besides BDNF, we did not investigated the other members of the neurotrophin family which also includes Nerve Growth Factor (NGF), Neurotrophin-3 (NT-3) and Neurotrophin-4/5 (NT-4/5) because the available data indicate that they are not useful as biomarkers of anxiety." (PMID 26539329, 2015).
breast carcinoma (8 papers, 2012 to 2023). "Neurotrophin-3 (NT-3) is known to be involved in various cancers including breast cancer, lung cancer, and adenoid cystic cancer." (PMID 36430813, 2022). "A study of NTRK2 and anoikis in breast cancer cell lines also showed that miR-200c can directly target neurotrophin 3 (NTF3) and this NTRK2/NTF3 signaling is the downstream effector of NFKB signaling which promotes anoikis." (PMID 27601996, 2016). "To determine if BDNF or NTF3 activate TrkB signaling in a breast cancer model, we stably transfected empty vector (EV) or TrkB into MCF7 and T47D cells." (PMID 23185507, 2012). "We present the first evidence that, in breast cancer, endogenous NTF3 is secreted upon suspension to enable TrkB-mediated anoikis resistance." (PMID 23185507, 2012). "Our findings uniquely demonstrate that, in anoikis resistant breast cancer cells, NF-κB transcriptional activity increases to mediate direct up-regulation of TrkB, and its ligand, NTF3 setting up an aberrant autocrine signaling loop." (PMID 23185507, 2012). "Having shown that the combination of TrkB and NTF3 is sufficient to induce anoikis resistance in luminal breast cancer cells, we sought to determine if TrkB and NTF3 are necessary for TNBC cells to resist anoikis." (PMID 23185507, 2012). "Taken together, our findings define a critical mechanism for transcriptional and post-transcriptional control of suspension-induced up-regulation of TrkB and NTF3 in anoikis resistant breast cancer cells." (PMID 23185507, 2012). "Furthermore, neurotrophin-3 modulates breast cancer cells and the microenvironment to promote breast cancer brain metastasis." (PMID 37566075, 2023). "Finally, a growth factor expressed by all of the OERCs of tumor cells—i.e., neurotrophin-3 (NTF3)—was related to brain metastasis in breast cancer." (PMID 35205840, 2022). "Specifically, our discovery of suspension-induced up-regulation of TrkB and NTF3 in breast cancer cells via NF-κB supports earlier work showing that polo-like kinase 1 (PLK1) is transcriptionally activated by RelA in suspended esophageal squamous cell carcinomas, leading to anoikis resistance." (PMID 23185507, 2012). "Neurotrophin 3 (NTF3) is a member of the nerve growth factor (NGF) family that is involved in the progression of various cancers, including medulloblastoma, primitive neuroectodermal brain tumors, and breast cancer." (PMID 36263167, 2022). "Thus, in breast cancer cells, NTF3 is capable of activating TrkB to induce anoikis resistance to the same extent as BDNF, supporting our hypothesized role of NTF3 in TrkB-mediated anoikis resistance." (PMID 23185507, 2012).
hearing loss (7 papers, 2014 to 2025). "Further animal studies have suggested neurotrophin-3 to protect against this type of noise-induced synaptic damage, and to facilitate synaptic recovery following noise exposure-induced hearing loss." (PMID 34847940, 2021). "For Ntf3 to be a viable candidate to treat noise-induced hearing loss, it must be effective even if applied after noise exposure." (PMID 25329343, 2014). "This was supported by the finding that neurotrophin-3 could increase the synapse density between SGNs and HCs, which had a protective effect on hidden hearing loss." (PMID 40332354, 2025). "Another study that employed a similar approach described the protective effects of neurotrophin 3 (NT-3), and AAV-mediated NT-4–activity-dependent neurotrophic factor 9 (ADNF-9) overexpression was found to be protective against kanamycin-induced hearing loss." (PMID 35667089, 2022).
spinal cord injury (7 papers, 2014 to 2023). Penetrating and non-penetrating injuries to the spinal cord resulting from traumatic external forces (e.g., WOUNDS, GUNSHOT; WHIPLASH INJURIES; etc.). "Muscle spindles synthesize neurotrophin-3 and this may be one of the feedback signals in proprioceptive neurons underlying spontaneous recovery after spinal cord injury." (PMID 27759565, 2016). "Here we investigated whether targeted delivery of neurotrophin-3 (NT-3) to lumbar motoneurons (MNs) caudal to a thoracic (T10) contusive spinal cord injury (SCI) could modulate dendritic patterning and synapse formation of the lumbar MNs." (PMID 30207538, 2018). "Nerve growth factor (NGF), glial cell line-derived neurotrophic factor (GDNF), brain derived neurotrophic factor (BDNF) and neurotrophin-3 (NT-3) have all been added to biomaterials to treat TBI as well as neurodegenerative disorders spinal cord injuries and peripheral nerve injuries." (PMID 26056586, 2014).
Stroke (7 papers, 2016 to 2023). Sudden impairment of blood flow to a part of the brain due to occlusion or rupture of an artery to the brain. "We show here that intramuscular delivery of neurotrophin-3 (NT3, encoded byNTF3) can induce sensorimotor recovery when treatment is initiated 24 h after stroke." (PMID 26614754, 2016). "Ongoing work in our laboratory seeks to identify the optimal biopharmaceutical delivery route and form (protein, gene therapy, agonist antibody or small synthetic molecule) for neurotrophin-3 and for targeting its receptors after spinal cord injury and stroke." (PMID 27759565, 2016). "This time-frame would be clinically feasible for most stroke victims, and the safety and tolerability of neurotrophin-3 in humans have been established for other disorders." (PMID 26614754, 2016). "In previous studies, our group used delayed, intramuscular neurotrophin-3 to treat stroke and observed improved fine motor function and tactile sensation in adult and elderly rats." (PMID 27759565, 2016). "Recent studies from our group show that peripherally administered Neurotrophin-3 can remodel spared corticospinal tract connections and promote sensorimotor recovery in adult and elderly rats after stroke." (PMID 27759565, 2016). "Durickiet al.show that intramuscular delivery of human neurotrophin-3 induces corticospinal plasticity and locomotor recovery in adult and elderly rats 24 hours post-stroke." (PMID 26614754, 2016). "Furthermore, another ligand of the TrkA receptor is neurotrophin-3, which has been studied to attenuate immune inflammatory response after stroke and limit cell death." (PMID 37508918, 2023). "This indicates that neurotrophin-3 has potential applications in the treatment of stroke." (PMID 32714405, 2020). "In animal studies, neurotrophin-3 may promote sensory and motor function recovery after stroke." (PMID 32714405, 2020).
hepatocellular carcinoma (6 papers, 2021 to 2024). A malignant tumor that arises from hepatocytes. "Yang et al48 reported that NTF3 was downregulated in hepatocellular carcinoma and that its low expression activates the MAPK pathway." (PMID 38769659, 2024). "Our analysis identified significant structural and expressional changes in Neurotrophin 3 (NTF3), known as a tumour suppressor in hepatocellular carcinoma that promotes apoptosis through the MAPK pathway." (PMID 38769659, 2024). "NTF3 also had a significant correlation with prognosis and immune infiltration in hepatocellular carcinoma." (PMID 38049825, 2023). "NTF3 is under-expressed in human hepatocellular carcinoma (HCC), albeit its specific effects and the action mechanism have not been elucidated." (PMID 36263167, 2022). "Therefore, we aimed to explore the clinical value of NTF3 in hepatocellular carcinoma (HCC)." (PMID 34938753, 2021). "Furthermore, several studies have shown that the NTF3 can bind to the p75 neurotrophin receptor and activate the P38 MAPK pathway to promote apoptosis, which may inhibit the development of hepatocellular carcinoma." (PMID 38678587, 2024).
glioma (5 papers, 2016 to 2024). A benign or malignant brain and spinal cord tumor that arises from glial cells (astrocytes, oligodendrocytes, ependymal cells). "Moreover, the reduced expression patterns of stemness-associated genes (MYC and SOX2) and the reactivation of neuronal differentiation-associated genes (BDNF, NGF, and NTF3) were clearly observed in the asTUG1/uPIC-treated glioma tissues." (PMID 31019193, 2019). "Certain chemokines and growth factors, including vascular endothelial growth factor (VEGF), interleukin-8 (IL-8), transforming growth factor-β (TGF-β), and neurotrophin-3 (NT-3) released from mature glioma cells, have been reported to mediate the tropism of MSCs for gliomas." (PMID 30413179, 2018). "Some of the genes defined as REST-activated targets (i.e. NTF3 and GLI3) containing KAISO motifs within the REST ChIP-seq peaks had a methylation pattern similar to the repressed REST targets across glioma tumor types." (PMID 38711090, 2024). "In the RMPAlow gliomas, a different set of RTK signaling-related genes including MET (8.9%), EPHA1 (8.9%), EPHB6 (8.9%), EPHB4 (8.3%), BRAF (8.9%), FGF6 (11.9%), FGF23 (11.9%), NTF3 (11.9%), and ANGPT1 (9.5%) were amplified." (PMID 27385209, 2016).
schizophrenia (5 papers, 2007 to 2024). A major psychotic disorder characterized by abnormalities in the perception or expression of reality. "For example, a dinucleotide polymorphism (CA23) in the A3/147 bp NTF3 promoter region was found to be associated with schizophrenia in a Japanese population." (PMID 38646100, 2024). "A statistically significant association between the frequency of NTF3 gene SNP rs1805149-A (G76E) and the incidence of schizophrenia was found only in patients with the early manifestation (earlier than 25 years-old) and patients with a significant duration of the disease (more than 10 years)." (PMID 38646100, 2024). "This research proposes a peripheral biomarker for schizophrenia that involves the second extracellular loop of norepinephrine transporter (NEText), the tropomyosin receptor kinase C (TrkC), and the neurotrophin-3 (NT-3) in T cells." (PMID 34445205, 2021).
Cognitive impairment (4 papers, 2021 to 2024). Abnormal cognition is characterized by deficits in thinking, reasoning, or remembering. "Some polymorphisms of the NTF3 gene turned out to be associated with the incidence of psychiatric and cognitive disorders, although they appear to have different significance in different populations." (PMID 38646100, 2024). "Despite the importance of NT-3 in brain morphogenesis, the association of genomic variants of NTF3 with predisposition to mental and cognitive disorders only in limited and narrow selections, which leaves the role of NTF3 SNPs in psychiatric diseases in question." (PMID 38646100, 2024). "Hippocampal brain-derived neurotrophic factor (BDNF) or Neurotrophin-3 (NT-3) microinjection could partially improve the sevoflurane-induced cognitive impairment and AHN inhibition, respectively." (PMID 35309893, 2022).
endometriosis (4 papers, 2019 to 2025). The growth of functional endometrial tissue in anatomic sites outside the uterine body. "NGF and neurotrophin-3 (NT-3), are expressed in peritoneal endometriotic implants and in the peritoneal fluid of patients with endometriosis." (PMID 40948761, 2025). "The expression of several molecules with neurotrophic effects, including the nerve growth factor, neurotrophin-3 and the brain-derived neurotrophic factor, has been reported in women with endometriosis." (PMID 31491902, 2019). "TGF-ß1 is known to affect the expression of growth factor (NGF) and neurotrophin-3 (NT-3) mRNA, and as ILK remains under TGF-ß1 control, the involvement of ILK in the mechanism of pelvic pain in women with endometriosis is therefore possible." (PMID 36768775, 2023).
pancreatic cancer (4 papers, 2019 to 2024). "Upregulated NTF-3 was observed in other tumor cells, for example, in pancreatic carcinoma tissue compared to normal pancreatic tissue." (PMID 39408891, 2024). "It was showed that neurotrophin-3 mRNA elevated in pancreatic cancer tissues in patients with perineural invasion." (PMID 31602269, 2019). "It has been observed that MiR-429 upregulation substantially suppresses the neurotrophin-3 mRNA andsecretion in pancreatic cancer cells." (PMID 31602269, 2019).
Parkinson disease (4 papers, 2013 to 2024). A progressive degenerative disorder of the central nervous system characterized by loss of dopamine producing neurons in the substantia nigra and the presence of Lewy bodies in the substantia nigra and locus coeruleus. "We previously demonstrated that PAMs delivering neurotrophin-3 can improve MIAMI cells survival, thereby preserving neural function in a Parkinson’s disease animal model." (PMID 31614758, 2019).
diabetes (3 papers, 2020 to 2021). "Moreover, the correlation between NTF3 and diabetes mellitus has been identified." (PMID 32694937, 2020).